CDCA3 (cell division cycle associated 3)
Diseases named in the same sentence as CDCA3 in open-access papers (continued):
Sharing a sentence is not in itself a finding about the gene and the disease.
tumor (continued). "Simultaneously, we observed that miR-4677-3p expression was increased, while CDCA3 expression was reduced in the stripped tumor tissues of circ_0001421 decreased group." (PMID 33109222, 2020). "Circ_0001421 promoted cell proliferation, migration, invasion and glycolysis in LC by regulating the miR-4677-3p/CDCA3 axis, which providing a new mechanism for LC tumor progression." (PMID 33109222, 2020). "Among the clinical classifications, CDCA3-positive OSCCs were correlated significantly (*p < 0.05) with tumor size." (PMID 22839099, 2012). "Among the clinical variables analyzed, the CDCA3 expression status was closely related to tumor size (p < 0.05)." (PMID 22839099, 2012). "Additionally, in vivo experiments demonstrate that silencing CDCA3 inhibits T24 BLCA tumor growth, whereas intraperitoneal injection of pyruvate restores the proliferation of sh-CDCA3 T24 cells." (PMID 39980052, 2025). "ZWINT, HASPIN, and CDCA3 are all expressed in tumor cells to promote proliferation." (PMID 40416783, 2025). "Combining the clinicopathologic data from TCGA and TNMplot, and the IHC analysis from 74 patients, it was showed that the expression level of CDCA3 was aberrantly elevated in PC tumor tissues compared with that in the adjacent peritumoral tissues, and was negatively associated with patient survival." (PMID 40822457, 2025). "Notably, CDCA3 was found to interact with CDK1, and CDK1 overexpression negated the tumor-suppressive effects of CDCA3 downregulation." (PMID 40969596, 2025). "In addition, lncRNA SNHG12 increased CDCA3 expression and thus mediated tumor progression and sunitinib resistance in RCC patients." (PMID 37064095, 2023). "In conclusion, CDCA3 was closely related to tumor immune cells infiltration and antitumor immunity." (PMID 36213833, 2022). "As shown by the GSEA results, high levels of CCP-related gene expression were shown by GSEA to trigger DNA replication, the G1-S specific transcription factor, the mitotic spindle checkpoint, and cell cycle progression, which demonstrates that CDCA3 is a regulator of tumor cell cycle progression." (PMID 36713580, 2022). "CDCA3 has been suggested to influence the NF-κB pathway to mediate tumor progression." (PMID 36213833, 2022). "CDCA3 may participate in the regulation of immune infiltration in tumor microenvironment by affecting the expression of many immune regulatory factors and TMB, which is expected to provide valuable reference for clinical ICIs treatment." (PMID 36213833, 2022). "Furthermore, we constructed receiver operating characteristic (ROC) curves, and the area under the curve (AUC) for CDCA3 was 0.867, which indicates that CDCA3 is significantly differentially expressed in tumor and normal tissue." (PMID 36713580, 2022). "Interestingly, in contrast to our findings, upregulation of CDCA3 in other tumour types is reported to contribute to therapy resistance." (PMID 34572879, 2021). "Therefore, herein, we focused on determining the effects of CDCA3 expression on immune infiltration that contributes to the tumor microenvironment." (PMID 33604380, 2021). "Accordingly, it is possible that strategies to upregulate CDCA3 levels, particularly in CDCA3low tumours or upon the emergence of therapy resistance, might improve the response to EGFR TKIs and benefit patients." (PMID 34572879, 2021). "The expression of CDCA3 was up-regulated in a variety of tumor tissues." (PMID 34905505, 2021). "CDCA3 expression might influence the tumor immune infiltration microenvironment by regulating the levels of immune infiltration cells." (PMID 33604380, 2021). "Molecular biology experiments revealed that silencing the expression of CDCA3 could impair the migration ability of tumor cells and inhibit tumor cell growth via arresting cells in the G1 cell cycle phase." (PMID 33980246, 2021). "Thus, CDCA3 can lead to poor prognosis through the modulation of immune escape and immunosuppression effects and regulation of tumor-infiltrating immune cells." (PMID 33604380, 2021).
tumor (continued). "Collectively, these findings indicated that CDCA3 expression modulated the immune escape and immunosuppressive effects and regulated the tumor-infiltrating immune cells in the tumor progression, thereby demonstrating its potential as a prognostic biomarker for HCC." (PMID 33604380, 2021). "However, CDCA3 has been identified in network analysis to contribute toward enabling tumours to cope with high levels of genome stability." (PMID 34050247, 2021). "Moreover, a higher expression of the CDCA3 and UBE2C genes was significantly associated with higher tumor histologic grades." (PMID 34577856, 2021). "Additionally, the tumor-suppressive effect induced by circUBE2D2 depletion was greatly impaired upon miR512-3p down-regulation or CDCA3 overexpression." (PMID 32944002, 2020). "Additionally, CDCA3 expression was inversely associated with miR-512-3p expression, while was positively correlated with circUBE2D2 expression in TNBC tumor tissues." (PMID 32944002, 2020). "Overall, we found that SNHG12 promoted tumour progression via CDCA3 in RCC cells." (PMID 32641718, 2020). "Additionally, CDCA3 has been found to be upregulated in ovarian and endometrial cancers, contributing to the aggressive phenotype by facilitating rapid cell division and enhancing tumor cell survival." (PMID 40114265, 2025). "In vitro studies revealed that silencing CDCA3 could impair the migration ability of tumor cells via down-regulating EMT-related proteins such as MMP9 and Vimentin and inhibit tumor cell growth via arresting cells in the G1 cell cycle phase through regulating cell cycle related proteins like p21." (PMID 33980246, 2021). "Higher expressions of CDCA3 and UBE2C were significantly associated with higher histologic grades, but not with other clinical features, including age, clinical stage, lymphatic invasion, venous invasion, primary therapy outcome, personal tumor status, and vital status." (PMID 34577856, 2021). "Furthermore, CDCA3 expression possibly influences the proliferation of tumor cells." (PMID 33604380, 2021). "In addition, CDCA3 protein expression levels in primary OSCCs were correlated with tumor size." (PMID 22839099, 2012). "In BLCA, CDCA3 overexpression is driven by MYBL2 activation, underscoring its role in tumor progression." (PMID 39980052, 2025). "In conclusion, this study provides strong evidence that curcumin exerts its anticancer effects in CRC by modulating the miR-134-5p/CDCA3/CDK1 axis, thereby suppressing tumor cell proliferation and invasion and promoting apoptosis." (PMID 40969596, 2025). "For example, CDCA2, CDCA3, and CDCA8 exhibited moderate positive correlations with the immune checkpoint CD276, suggesting that higher CDCA expression might be associated with increased levels of CD276, potentially aiding immune evasion in the tumor microenvironment." (PMID 40114265, 2025). "Across CDCA2, CDCA3, CDCA4, CDCA5, CDCA7, and CDCA8, we observed significantly lower promoter methylation levels in primary tumor samples compared to normal samples, suggesting hypomethylation of these genes in GBM tumors." (PMID 40114265, 2025). "Our findings revealed that the expression levels of the hub genes—UBE2T, KIF4A, CDCA3, and CDCA5—were correlated with various clinical aspects of HCC, including cancer stages, nodal metastasis status, tumor grade, and histological subtypes." (PMID 38890649, 2024). "As the results indicated, the expressions of CDCA3, MYCN and TFAP2A in ccRCC tumor tissue were significantly upregulated compared with those in adjacent normal kidney tissue, while the expressions of ACADSB and CHAC1 were significantly downregulated." (PMID 37064095, 2023). "CDCA3 presents as a good biomarker candidate to predict the prognosis of RCC patients and potentiates the immune tumor microenvironment (TME) of RCC." (PMID 36213833, 2022). "Scholars reveal that CDCA3 was upregulated in RCC and promote tumor progression and sunitinib resistance via activating the NF-κB/cyclin D1 signaling axis." (PMID 36213833, 2022).
tumor (continued). "We chose the type of cancer whose expression of CDCA3 showed a strong correlation with both the patients' prognosis in GEPIA and tumor purity in TIMER." (PMID 33604380, 2021). "We next assessed CDCA3 transcript levels by bioinformatics analysis of TCGA datasets of LUAD NSCLC comparing EGFR wild-type and mutant tumours." (PMID 34572879, 2021). "Then we can find there are 65 “good genes” among them, and most of 65 “good genes” are negatively correlate with tumor stage, while the only 4 “bad genes” (CDC20, CDCA3, FBXL6, UBE2C) are positively correlate with tumor stage." (PMID 34093816, 2021). "We found that both CDCA3 and FOL1 have clear tumor-promoting effects in a variety of tumors and both play key roles in the regulatory mechanisms, which is consistent with previous studies." (PMID 34430085, 2021). "In tumours and EGFR mutant cell lines, we further identified that CDCA3 correlates with sensitivity to TKI." (PMID 34572879, 2021). "We also identified that CDCA3 levels were significantly higher in ADC and SqCC tumours with features of abnormal chromosome count, termed aneuploidy, versus diploid tumours." (PMID 34050247, 2021). "Here, we demonstrated that CDCA3 was differentially expressed between the tumor tissues and corresponding normal tissues using in silico analysis in the ONCOMINE and Tumor Immune Estimation Resource (TIMER) databases." (PMID 33604380, 2021). "After comparing the expression level of the tumor tissue and the paracancer tissue in each case, we found that the expression levels of CDCA2, CDCA3, CDCA5 and CDCA8 were overexpressed in tumor tissues in each patient." (PMID 32913466, 2020). "This study reported that CDCA3, CDCA5, and CDCA8 mRNA expression levels were significantly higher than the control sample in both clinical tumor sample and cancer cell lines, which dramatically reduced patient survival." (PMID 33285689, 2020). "CDCA3, CDCA5, and CDCA8 mRNA expression levels were significantly higher than the control sample in both clinical tumor sample and cancer cell lines." (PMID 29467944, 2018). "Notably, when PCA was repeated using only the six prognostic genes (AQP4, CDCA3, HJURP, KIF20A, PLK1, UHRF1), tumour and normal samples remained partially separable." (PMID 41007424, 2025). "Similarly, MYBL2 promotes cell cycle progression by transactivating targets, such as CDCA3, and interacting with FOXM1 to potentiate Wnt signaling, thereby further promoting tumor progression." (PMID 41439026, 2025). "Similarly, there were significant expression differences for RDM1, CDCA3 and FLVCR1 within different tumor stages." (PMID 41048998, 2025). "LncRNA SNHG12 could activate CDCA3 expression by stabilising SP1, thereby promoting tumour progression." (PMID 39999286, 2025). "Furthermore, CDCA3 high expression was significantly positive related to PSA, tumor stage and Gleason score." (PMID 37682152, 2023). "Moreover, hsa_circ_101555 functions as a tumor promotor and is required to sustain the proliferation and invasion of HCC by directly binding to miR-145-5p and impeding its suppression of CDCA3." (PMID 33824281, 2021). "In summary, we demonstrated for the first time that long noncoding RNA SNHG12 could upregulate the expression of CDCA3 by stabilising the transcription factor SP1 and thereby promoting tumour progression and sunitinib resistance in RCC." (PMID 32641718, 2020). "Additionally, our study indicated that CDCAs (i.e., CDCA1, CDCA3–6, and CDCA8) have significant hypomethylation levels in tumor tissues of HCC." (PMID 33665158, 2020). "Notably, CDCA3, CDCA4, CDCA5, and CDCA8 exhibited elevated expression trends in the radiation-resistant cohorts, consistent with the TCGA-READ database findings showing preferential CDCA family overexpression in tumor specimens." (PMID 40565588, 2025). "Whether there may be tumour type-specific roles or differences in mechanisms regulating CDCA3 transcription or protein levels between tumour types is not yet clear." (PMID 34572879, 2021).
tumor (continued). "Moreover, Kaplan–Meier survival analysis showed that a higher expression of CDCA3 and UBE2C was associated with poor overall patient survival regardless of tumor stage and a higher tumor histologic grade." (PMID 34577856, 2021). "Additionally, when using Kaplan–Meier survival analysis, it became clear that higher levels of CDCA3 and UBE2C together were linked to poorer survival outcomes for patients, regardless of the stage of the tumor or how advanced the tumor appeared under the microscope." (PMID 38577722, 2024). "Several studies have revealed the oncogenic role of NUF2, CDCA3, and KIF14 in tumor, but the mechanism has not been elucidated." (PMID 34699322, 2021). "Similarly, CDCA3 and HJURP displayed reproducible negative correlations with distinct NSC derivatives (e.g., NSC685416, NSC709900), consistent with enhanced drug sensitivity in tumours with elevated expression." (PMID 41007424, 2025).
cancer (39 papers, 2007 to 2025). A tumor composed of atypical neoplastic, often pleomorphic cells that invade other tissues. "And it has been widely evidenced in multiple human cancers that silencing Cdca3 would cause cell cycle arrest and block cell proliferation." (PMID 38369486, 2024). "High expression of CDCA3 was associated with poor outcome for patients with various cancers, and elevated CDCA3 expression led to poor OS, RFS, PFS, and DSS in HCC." (PMID 33604380, 2021). "Altogether, the overexpression of CDCA3 is likely associated with cell cycle arrest at the G1 phase, a critical checkpoint for cell division, resulting in a chain reaction of descending processes that likely leads to the development of cancers." (PMID 29467944, 2018). "CDCA3 has been associated with both cancer risk and poor prognosis in certain tumors." (PMID 28423514, 2017). "Intersectional analysis revealed CDCA3 as an interesting gene, consistently correlated across 33 cancer types." (PMID 38577722, 2024). "CDCA3 correlation with UBE2C across all TCGA cancers highlights its potential significance in diverse contexts." (PMID 38577722, 2024). "In HCC, E2F4 was significantly increased and promoted cancer progression via transcriptionally upregulating CDCA3 expression." (PMID 39309426, 2024). "Investigating the differential expression of CDCA3 between human tumors and normal tissues, the expression levels of CDCA3 in pan-cancer were analyzed using the TCGA database." (PMID 37682152, 2023). "We verified the four up-regulated lncRNAs (TCONS_00020615, TCONS_00055555, TCONS_00106091, and TCONS_00130858) and eight cancer-related mRNAs (CDCA3, DIAPH3, MCM7, NCAPG2, TPD52, PRC1, SETD6, and KIF22) involved in the ceRNA network by qRT-PCR." (PMID 37098483, 2023). "As previously demonstrated, AURKB was correlated with FAM64A, PRAME, CDCA3, etc., which are all highly related to cancers." (PMID 33612479, 2021). "We used the Kaplan–Meier plotter database to evaluate the interaction between CDCA3 expression and prognosis in various human cancers." (PMID 33604380, 2021). "We also used GEPIA to assess the relationship between CDCA3 expression and prognosis of the patients in 33 different TCGA cancer types." (PMID 33604380, 2021). "In our research RMI2 interacts with cell division cycle-associated protein 3 (CDCA3) and cyclin B2 (CCNB2), which are also related with malignant tumors." (PMID 33083148, 2020). "Through enhancing cell proliferation with the prevention of G1 phase arrest, the upregulation of CDCA3 promoted cancer progression." (PMID 33665158, 2020). "In another bioinformatics study of 2158 full cancer transcriptomes from 163 diverse entities, CDCA3 was proven to be a novel gene involved in liver carcinogenesis." (PMID 29467944, 2018). "Significantly, by combining our previous research with the construction of chemoresistant PC cell lines, the perplexing protein interactions between CDCA3 and NF-κB a cancer-related signaling pathway were illustrated in present study, that is CDCA3/TRAF2/NF-κB axis." (PMID 40822457, 2025). "In addition, a subset of these genes has been associated with cancer therapy responses (AZU1, CDCA3, CEACAM6, EN1, PF4)." (PMID 35008420, 2022). "The cell division cycle associated protein 3 (CDCA3) mainly participates in drug resistance and cell cycle regulation in cancers and has not been studied in depth." (PMID 36230613, 2022). "Studies have suggested increased CDCA3 expression in many cancer types." (PMID 36713580, 2022). "There has also been evidence of increased CDCA3 expression in many cancer types." (PMID 36713580, 2022). "These evidences suggest an important role of CDCA3 in promoting cancer in a variety of tumors." (PMID 34430085, 2021). "We supposed that CDCA3 may affect the carcinogenic process of human cancer by influencing the cell cycle." (PMID 33604380, 2021).
cancer (continued). "Although this study clarifies that hsa_circ_101555 functions as a sponge of miR-145-5p to promote CDCA3-induced HCC cancer cell proliferation and invasion, circRNAs may regulate the development and progression of HCC via other mechanisms." (PMID 33824281, 2021). "We explored the relationship between the infiltration levels of immune cells and CDCA3 expression in 39 types of human cancer using the TIMER database, where the value of “partial cor” reflected the degree of correlation between CDCA3 expression and immune infiltration." (PMID 33604380, 2021). "It was worth noting that CDCA3 negatively regulated the inflammation in several types of cancers." (PMID 32913466, 2020). "Further studies to identify the interaction between CDCA3 and SCF and additional substrates for cell division cycle genes and to determine how CDCA3 is dysregulated in various cancers and the functional role of CDCA3 during oral carcinogenesis might reveal novel mechanisms for cell-cycle regulation." (PMID 22839099, 2012). "Subsequently, the expressions of CDCA2, CDCA3, CDCA4, CDCA5, CDCA7, and CDCA8 genes in COAD samples across various cancer stages were verified using the GEPIA2 database." (PMID 39924497, 2025). "Co-expression network analysis showed that CDCA3, GSG2, KIF2C, NCAPH and PLK1 were positively correlated with ORC1 in cancer, and the functional enrichment mainly included cytosol, ATP binding and cell division." (PMID 37833711, 2023). "Co-expression network analysis showed that CDCA3, GSG2, KIF2C, NCAPH and PLK1 were positively correlated with ORC1 in cancer, and enrichment analysis showed a correlation with cytosol, ATP binding and cell division." (PMID 37833711, 2023). "Intriguingly, previous studies have shown that these molecules can contribute to the progression of a variety of cancers, with PTTG1 and CDCA3 being found to be prognostic biomarkers for KIRP." (PMID 37004005, 2023). "Among them, seven genes of CDCAs (CDCA1/NUF2: P = 2.73E-22, CDCA2: P = 1.52E-16, CDCA3: p = 1.50E-20, CDCA5: P = 1.77E-20, CDCA6/CBX2: P = 6.87E-19, CDCA7: P = 5.92E-16, and CDCA8: P = 1.67E-18) were all up-regulated in 19 cancer datasets." (PMID 33665158, 2020). "FOXM1 (FC = 1, FDR = 6.7e-06) and CDCA3 (FC = 1.2, FDR = 6.3e-07) are two representative genes overexpressed in late stage cancer, which also had high correlation coefficients between CNV and expression level (R = 0.70 and R = 0.54, respectively)." (PMID 25648588, 2014). "CDCA3 was found as a UBE2C correlated gene, which is common in 30 types of TCGA cancers." (PMID 38577722, 2024). "Additionally, the absence of significant differences in the mRNA expression levels of CDCA2, CDCA3, CDCA4, CDCA5, CDCA7, and CDCA8 across different cancer stages of COAD suggests that these genes may play a consistent role throughout the progression of COAD." (PMID 39924497, 2025).